MDM2 (MDM2 proto-oncogene)
Diseases named in the same sentence as MDM2 in open-access papers (continued):
Sharing a sentence is not in itself a finding about the gene and the disease.
tumor (continued). "However, abemaciclib-treated hormone receptor-positive breast cancer patients with tumor-associated mdm2 gene copy gains or pronounced HER4 expression showed a reduced event-free survival." (PMID 39000582, 2024). "MYC and MDM2 are involved in inflammation and fibrosis and are associated with tumor proliferation." (PMID 39618816, 2024). "However, studies evaluating MDM2 splicing variant functions regarding tumor development have been inconclusive." (PMID 39769278, 2024). "In a study published by Mangiola and colleagues, several tumor‐associated alterations were present in brain adjacent to the tumor area, as well as in the TC: del(1p36), del(2p21), MDM2 and CDK4 amplification, amplification of 15q24.1, chromosome 19 and 22 losses." (PMID 36300592, 2023). "Tumor cells showed amplification of MDM2 gene and a homozygous loss of CDKN2A on 9p21." (PMID 37818167, 2023). "MDM2 proto-oncogene (MDM2) gene encodes a nuclear-localized E3 ubiquitin ligase which could enhance tumor formation by influencing tumor suppressors, such as p5326." (PMID 37095178, 2023).
tumor (continued). "Furthermore, in response to vHMW-HA activation, NMRs create a unique tumor suppressor molecule, which encodes mammalian tumor suppressors: the cyclin-dependent kinase inhibitors p15, p16, as well as p19, a repressor of the MDM2 oncogene." (PMID 36613567, 2022). "Importantly, MDM2 amplification in solid tumors has been associated with the paradoxical tumor hyper-progression seen in patients who receive PD-1/PD-L1 checkpoint blockade." (PMID 36136862, 2022). "It has been reported that MDM2 rs2279744 polymorphism, a functional T to G mutation in the promoter region, can significantly accelerate tumor formation, indicating that the mutated allele G may be a powerful cancer susceptibility allele." (PMID 36059664, 2022). "Notably, a lower expression of MDM2 in tumor biopsies after treatment with palbociclib was associated with tumor response." (PMID 36119484, 2022). "The tumor equivocally stained for MDM2 and CDK4 and negatively for S100, with loss of H3K27me3." (PMID 33580196, 2021). "In addition, TRIM31 deficiency-mediated increased tumor growth was abolished by the knockout of MDM2." (PMID 34650049, 2021). "However, it has also been shown that exosomes released from MSCs transfer mRNA encoding CXCR4, VEGF, α-SMA, and MDM2 to tumor cells, thus enhancing angiogenic activity and tumor growth." (PMID 32499786, 2020). "Meanwhile, given that MDM2 acts as a tumor-associated antigen, immunological tolerance might also promote HPD induced by MDM2 overexpression." (PMID 33195412, 2020).
tumor (continued). "As such, our experimental approach allowed us to interrogate the metabolite and lipid differences that could underlie the heightened chemoresistance of MDM2 higher tumor cells as compared to lower." (PMID 32759684, 2020). "STRING and Cytoscape were used to determine whether the BIRC5 and its associated tumor transcription factors predicted before were functionally related to MDM2." (PMID 33195412, 2020). "Higher MDM2 protein expression also results in an increased risk for spontaneous tumour formation." (PMID 32951327, 2020). "The MDM2 mutation also makes normal cells more susceptible to transformation, causing tumor growth." (PMID 32425780, 2020). "A single nucleotide polymorphism identified in the MDM2 promoter may enhance MDM2 expression that contributes to tumor susceptibility." (PMID 32824373, 2020). "So far, more than 40 alternatively spliced variants of MDM2 gene transcripts have been identified in various tumor cells, but it is unknown at this time whether all of the splice variants are translated into protein." (PMID 30700046, 2019). "The analysis of tumor #2 revealed just one mutation (MDM2), seen in this one only." (PMID 30823914, 2019). "The MDM2 protein (also known in humans as Hdm2) may be the strongest inhibitor of apoptosis found so far, and it was described as one of the tumor associated antigens (TAA) as MDM2 was overexpressed in several kinds of tumor." (PMID 28147328, 2017). "Recent studies suggest that expression of splice variants of Mdm2 and Mdm4 may be similarly involved in tumor development." (PMID 28460439, 2017). "In the recent study, predominant expression of USP15 was found to be associated with a decrease in tumor cell apoptosis and antitumor T cell response, as evidenced by preventing ubiquitin-dependent degradation of MDM2 in melanoma and colorectal cancer cell lines." (PMID 28245560, 2017).
tumor (continued). "Another polymorphism on MDM2, 344 T > A SNP was identified in 2004 as accelerating tumor formation." (PMID 24708820, 2014). "Furthermore, a mouse bearing one of these mutations (Mdm2-C305F) was shown to have significantly accelerated tumor development in an Eμ-Myc mouse model." (PMID 23874713, 2013). "A recent meta-analysis indicates that MDM2 SNP309 serves as a tumor susceptibility marker." (PMID 23244604, 2012). "Moreover, the mdm2 SNP309 G allele associates with accelerated tumor formation in a gender-specific and hormone-dependent manner." (PMID 21223569, 2011). "On the basis of sixty-six case-control studies focused on MDM2 309 T/G polymorphism and tumor risk, our meta-analysis provided evidence that the variant homozygote GG and heterozygote TG were significantly associated with increased tumor risk." (PMID 21619694, 2011).
tumor (continued). "A T-to-G germline single nucleotide polymorphism in the promoter region of MDM2 (SNP309) has been reported to markedly accelerate tumor formation in humans suggesting that it may represent a powerful cancer predisposing allele." (PMID 21301048, 2010). "The recovery of some of the MDM4 variants, as well as of MDM2, in tumor cells and the analysis of their activity suggest that they may possess tumorigenic activity." (PMID 19721810, 2009). "Recent evidence from studies of milademetan in intimal sarcoma suggests that cyclin-dependent kinase inhibitor 2A (CDKN2A) loss and amplified twist-related protein 1 (TWIST1) may serve as additional biomarkers associated with enhanced anti-tumor activity in MDM2-amplified tumors." (PMID 41170373, 2025). "In summary, MDM2 might be associated with tumor proliferation and invasive behavior in NF-PitNETs." (PMID 36837574, 2023). "In a separate in vitro analysis, it was shown that combination MDM2 inhibition plus doxorubicin was associated with significantly reduced tumor growth compared with doxorubicin monotherapy, suggesting that the addition of MDM2 inhibition to conventional cytotoxic therapy might also be beneficial." (PMID 36439412, 2022). "Interestingly most patients with MDM2 amplification had a low Tumor Mutational Burden." (PMID 32265935, 2020). "Besides, immunological tolerance may also participate in the hyperprogressive disease induced by MDM2 overexpression given that MDM2 served as a tumor associated antigen (TAA) in malignancies." (PMID 31440117, 2019).